MCM7 (minichromosome maintenance complex component 7)
Diseases named in the same sentence as MCM7 in open-access papers (continued):
Sharing a sentence is not in itself a finding about the gene and the disease.
squamous cell carcinoma (7 papers, 2014 to 2022). A carcinoma arising from squamous epithelial cells. "Next, we investigated the clinicopathologic association of MCM4, MCM7, and Ki-67 expression in esophageal adenocarcinoma, squamous cell carcinoma, and precancerous lesions." (PMID 27476776, 2016). "Kaplan– Meier survival curves to analyze the difference between high and low expression level for MCM4, MCM7, and Ki-67 were generated based on overall survival in patients with esophageal adenocarcinoma and those with squamous cell carcinoma." (PMID 27476776, 2016). "The mean percentages of MCM4 and MCM7 expression were also high in squamous cell carcinoma (74% and 85%)." (PMID 27476776, 2016). "Our study investigated the correlation between MCM4 and MCM7 expression and Ki-67, Bmi1, and cyclin E expression in esophageal adenocarcinoma, squamous cell carcinoma, and precancerous lesions." (PMID 27476776, 2016). "Additionally, the percentages of MCM4, MCM7, and Ki-67 expression in squamous cell carcinoma were significantly greater than those in squamous epithelium." (PMID 27476776, 2016). "In epidermoid carcinoma (A431) cells and breast tumor samples LynA Y32 is phosphorylated by the epidermal growth factor receptor (EGFR), allowing it to phosphorylate MCM-7 and stimulate cell proliferation." (PMID 31282857, 2019). "The findings suggest that downregulation of MCM7, MAPT, TGFB2, and THBS1 by MS13 may inhibit cell proliferation and growth as well as metastasis and invasion in squamous cell carcinoma and adenocarcinoma NSCLC cells." (PMID 34299042, 2021). "Correlations between MCM4, MCM7, and Ki-67 expression and patients' clinicopathologic characteristics, including age, gender, TNM stage, and histologic grade, were analyzed in the adenocarcinoma group and the squamous cell carcinoma group." (PMID 27476776, 2016). "For MCM7, neither high (mean, 35.8 months) nor low (mean, 43.9 months) expression levels in the adenocarcinoma group and neither high (mean, 31.5 months) nor low (mean, 65.2 months) expression levels in the squamous cell carcinoma group demonstrated significant difference in overall survival." (PMID 27476776, 2016).
bladder cancer (5 papers, 2011 to 2025). "A member of this family, MCM7, has been shown to be up-regulated in numerous cancers including bladder cancer, especially in human papillomavirus (HPV)-positive tumors." (PMID 36672328, 2023). "Subsequently, immunohistochemical analysis using a bladder tissue microarray revealed that MCM7 was up-regulated in bladder cancer tissues at the protein level (21/29, 72.4%)." (PMID 21619671, 2011). "Suppression of MCM7 using specific siRNAs inhibited incorporation of BrdU in lung and bladder cancer cells overexpressing MCM7, and suppressed the growth of those cells more efficiently than that of normal cell strains expressing lower levels of MCM7." (PMID 21619671, 2011). "qRT-PCR revealed a higher expression of MCM7 in clinical bladder cancer tissues than in corresponding non-neoplastic tissues (P < 0.0001), and we confirmed that a wide range of cancers also overexpressed MCM7 by cDNA microarray analysis." (PMID 21619671, 2011).
meningioma (5 papers, 2020 to 2024). A generally slow growing tumor attached to the dura mater. "MCM7 is significantly associated with recurrence-free survival (P = 0.005) and obtains higher sensitivity in the ROC curve in meningioma than traditional marker MIB-1." (PMID 32089988, 2020). "Winther and Torp showed that the level of MCM7 protein expression was higher in Grade II meningiomas compared with Grade I meningiomas." (PMID 34144903, 2022). "Although only in single studies, KPNA2, CDK6, Cox-2, MCM7 and PCNA are proposed as additional markers with high expression that are related with poor prognosis of meningioma patients." (PMID 38758750, 2024).
ovarian cancer (5 papers, 2017 to 2021). A primary or metastatic malignant neoplasm involving the ovary. "Microliposome maintenance (MCM) 2, MCM3, MCM4, MCM5, MCM6, and MCM7 are DNA replication regulators and are involved in the progression of multiple cancer types, but their role in ovarian cancer is still unclear." (PMID 34178669, 2021). "Therefore, the results suggest a direct correlation between improved cell death and MCM7 expression and indicate that the selected combinations are valuable in opposing of Pt resistance in ovarian cancer." (PMID 33053689, 2020). "Interestingly, proteins such as CCNE1, FASN, HDGF, MCM7, PIGR, PTK2, or TRA2B have been described as having a prognostic relation with some other type of gynecological cancer (breast, cervical or ovarian cancer)." (PMID 34680205, 2021).
acute myeloid leukemia (3 papers, 2020 to 2022). Acute myeloid leukemia (AML) is a group of neoplasms arising from precursor cells committed to the myeloid cell-line differentiation. "The main objective of the study was to evaluate the associations between MCM7 rs2070215, rs1527423, and rs1534309 single nucleotide polymorphisms (SNPs) and acute myeloid leukemia (AML) risk and prognosis." (PMID 31936215, 2020). "Several studies have shown that overexpression of the MCM7 gene is associated with the appearance of certain neoplasms such as gastric, hepatic, or esophageal cancer, non-Hodgkin’s lymphoma, acute myeloid leukemia, and chronic myeloid leukemia." (PMID 31936215, 2020). "Recent studies have also shown that CDC45 regulated MCM7 in acute myeloid leukemia through the PI3K/AKT pathway, and another mechanism whereby replication partially disrupted eukaryotic DNA replication and triggered by ubiquitination of replication helicases." (PMID 36186452, 2022).
esophageal adenocarcinoma (3 papers, 2015 to 2022). A malignant tumor with glandular differentiation arising predominantly from Barrett mucosa in the lower third of the esophagus. "High CA9 expression was significantly associated with MCM4, MCM7 and Ki67 expression in esophageal adenocarcinoma and precancerous lesions." (PMID 26156831, 2015). "The mean percentages of MCM4 and MCM7 expression increased from squamous epithelium (6% and 7%) to columnar cell metaplasia (11% and 14%) and Barrett's esophagus (28% and 35%)." (PMID 27476776, 2016). "While MCM4 and MCM7 expression were located mainly at the base of glands in columnar cell metaplasia and Barrett's esophagus, their expression extended superficially to involve entire glands as the lesions progressed from dysplasia to adenocarcinoma." (PMID 27476776, 2016). "By microRNA microarrays and quantitative RT-PCR, MCM7 mRNA expression and DNA copy number at the MCM7 locus were found to be up-regulated and increased in esophageal adenocarcinoma with disease progression." (PMID 27476776, 2016). "Bmi1 is a stem cell marker with similar distribution to those of MCM4, MCM7, and Ki-67 in esophageal adenocarcinoma and precancerous lesions." (PMID 27476776, 2016). "Pairwise mean comparisons found the percentages of MCM4, MCM7, and Ki-67 expression in esophageal adenocarcinoma and high-grade dysplasia to be significantly greater than those in low-grade dysplasia, Barrett's esophagus, columnar cell metaplasia, and squamous epithelium (P < .05)." (PMID 27476776, 2016). "Finally, we analyzed the association of CA9 overexpression with BMI1, cyclin E, MCM4, MCM7 and Ki67 expression in esophageal adenocarcinoma." (PMID 26156831, 2015).
gastric tumor (3 papers, 2010 to 2023). "This amplicon contains two polycistrionic miRNA clusters, and the miR-106b-25 cluster, which is present in intron 13 of MCM7, was identified in the current investigation as being expressed in stomach tumours." (PMID 37594635, 2023). "A study found that MCM7 expression elevated with gastric tumor grade increasing and had a positive correlation with Ki-67 significantly." (PMID 32596300, 2020). "The miR-106b-25 cluster, up-regulated in a subset of human gastric tumors, is activated by E2F1 in parallel with its host gene, Mcm7." (PMID 23554630, 2010).
glioblastoma (3 papers, 2014 to 2021). The most malignant astrocytic tumor (WHO grade IV). "Knocking down MCM7 not only inhibits cell proliferation in glioblastoma multiforme tumor cells but also prevents tumor growth in mouse models of glioblastoma multiforme." (PMID 25386362, 2014).
lymph node metastasis (3 papers, 2011 to 2019). "There is evidence that high expression of MCM4 and MCM7 were associated with lymph node metastasis and shorter survival in EAC." (PMID 31380150, 2019). "Improved 5-year DFS was also associated with small tumour size and no lymph node metastases (P=0.004) and high MCM7-index (P=0.035)." (PMID 22333708, 2012).
medulloblastoma (3 papers, 2015 to 2022). A malignant, invasive embryonal neoplasm arising from the cerebellum. "In this study, overexpression of MCM2, MCM3, or MCM7 increased, and knockdown of these same genes decreased, the ability of medulloblastoma cells to migrate and invade." (PMID 35196311, 2022).
neuroblastoma (3 papers, 2020 to 2024). Neuroblastoma (NB) is the most common solid, extracranial childhood tumor. "MCM7 was over-expressed in different human cancers, including neuroblastoma, colorectal and prostate." (PMID 33053689, 2020). "From our final list of 104 genes, 3 of them (MCM4, MCM7, and TERT) have already been found to be deregulated for their expression in high-risk neuroblastoma, but the great majority (101 genes) have not." (PMID 37759629, 2023).
papilloma (3 papers, 2019 to 2021). A benign epithelial neoplasm that projects above the surrounding epithelial surface and consists of villous or arborescent outgrowths of fibrovascular stroma. "We also observed MCM7 induction in MmuPV-1-induced papillomas arising in mice expressing the Rb1L allele and in papillomas arising in animals infected with MmuPV1 genomes expressing the RB1-binding defective E7D90A mutant." (PMID 34465025, 2021). "Nevertheless, MmuPV1 can induce expression of MCM7, a strongly E2F-responsive gene, in vivo in the context of papillomas it induces." (PMID 34465025, 2021). "MCM7 expression was only up-regulated in upper proliferating keratinocyte layers of papillomas, CIS and SCCs." (PMID 31640696, 2019). "In SCCs, CIS and most papillomas, 10–90% of non-basal cells were positive for MCM7, depending on the degree of differentiation within the lesions." (PMID 31640696, 2019). "In non-basal keratinocyte layers, MCM7 expression was most often increased in papillomas, CIS and SCCs, depending on the degree of differentiation within the lesions." (PMID 31640696, 2019).
serous ovarian cancer (3 papers, 2016 to 2021). "One study found that MCM7 expression was associated with better prognosis in serous carcinoma of the ovary." (PMID 27476776, 2016). "The serous ovarian cancer dataset indicated that the percentages of DNA alterations of MCMs were 5% (MCM2), 4% (MCM3), 5% (MCM4), 2.6% (MCM5), 1.2% (MCM6), and 5% (MCM7)." (PMID 34178669, 2021).
skin cancer (3 papers, 2012 to 2021). "Consistent with the benign nature of this skin tumor, MCM7 expression in the basal layer was less evident, while it was highly expressed in the suprabasal cells overexpressing cytoplasmic E4." (PMID 29459852, 2018). "Additionally, in endometrial cancer and skin cancer studies, it was found that MCM4 mutations may affect the interaction with MCM7, thereby disrupting the stability of the MCM4/6/7 complex." (PMID 33564675, 2021). "MCM7 over-expression in epithelial progenitor cells sensitized mice to carcinogen-induced skin tumors but did not itself drive tumors by 1 year of age." (PMID 23133403, 2012).
viral infection (3 papers, 2017 to 2025). "The repression of MCM2, MCM3, MCM5, and MCM7 was associated with viral infection previously, but detailed functional studies have not been carried out." (PMID 28912786, 2017). "We analyzed reproductive tracts where epithelia showed histological hallmarks of virus infection for Ki67 and MCM7." (PMID 30837335, 2019). "Based on the clarification that the overexpression plasmid of MCM7 was successfully expressed in WRD cells, WRD cells were transfected with the pCMV-HA-MCM7 plasmid for 24 h before MVC viral infection." (PMID 41011485, 2025).
anal carcinoma (2 papers, 2008 to 2010). "Analysis of the association between MCM7 and CDKN2A (p16) protein expression, as accessed by IHC, and prognosis were performed on a separate cohort of anal carcinomas consisting of biopsies from 55 patients arranged in a tissue array." (PMID 18349847, 2008). "Following the results from the microarray analysis, CDKN2A (p16) and MCM7 were selected as a typical gene overexpressed in Gr2 to be investigated in an independent cohort of 55 anal cancer biopsies." (PMID 18349847, 2008). "However, we found that high expression of MCM7 in this cohort of anal carcinomas correlated with favourable clinical outcome (log-rank test, P=0.017 for probability of RFS and P=0.011 for probability of CSS), as illustrated in Figure 5Bb." (PMID 18349847, 2008). "While a high MCM7 protein staining was significantly associated with an improved CSS in 55 anal carcinoma patients treated with radiation with or without chemotherapy, presence of HPV mRNA assessed by ISH was not significantly related to survival in Kaplan–Meier analyses (log-rank test P=0.92)." (PMID 18349847, 2008). "Out of 62 anal carcinoma patients, 33.3% of those with a low MCM7 staining intensity (product <140) were HPV positive, as compared with 68.4% of those with a high MCM7 product (P=0.007, χ2 statistics)." (PMID 18349847, 2008). "Furthermore, we tested the associations between protein expression of two isolated target genes, MCM7 and CDKN2A (p16) with HPV E7 mRNA expression and with the clinical outcome in 55 anal cancer patients." (PMID 18349847, 2008). "High level of MCM7 protein was found to be associated with both improved relapse-free survival (RFS, P=0.02) and cancer-specific survival (CSS, P=0.03) in anal cancer patients treated with radiation with or without additional chemotherapy." (PMID 18349847, 2008).
chordoma (2 papers, 2011 to 2014). Chordomas are rare malignant tumors arising from embryonic remnants of the notochord in axial skeleton. "We performed quantitative PCR in chordoma cells using one set of primer/probes targeted to miRNAs and a reference control primer/probe set targeting MCM7 and RNaseP." (PMID 24621885, 2014).
Clear Cell Renal Cell Carcinoma (2 papers, 2021 to 2025). "First, to elucidate the expression of MCM7 in clear cell Renal Cell Carcinoma (ccRCC), we analyzed RNA and protein samples obtained from human ccRCC specimens." (PMID 40943553, 2025).
colon cancer (2 papers, 2019 to 2025). "In pancreatic ductal adenocarcinoma (PDAC), liver, breast, and colon cancers, MCM7 was shown to influence therapeutic response, supporting its promise as a potential therapeutic target." (PMID 40943553, 2025).
cutaneous melanoma (2 papers, 2016 to 2021). A primary melanoma arising from atypical melanocytes in the skin. "Inhibition of MCM7 can promote autophagy and apoptosis of skin melanoma cells." (PMID 34993142, 2021).
gastric adenocarcinoma (2 papers, 2022 to 2023). "Low MCM7 level can inhibit the proliferation and invasion of gastric adenocarcinoma cells, and high expression of MCM7 is associated with short survival, which can effectively predict prognosis, indicating that MCM7 is a potential biomarker and target for gastric adenocarcinoma." (PMID 35494047, 2022).
in situ carcinoma (2 papers, 2017 to 2021). A malignant epithelial neoplasm which is confined to the epithelial layer without evidence of further tissue invasion. "RACK1 and MCM7 expression were higher in in situ carcinoma and cancer cells than in normal bronchial epithelium cells." (PMID 28465488, 2017).
leukemia (2 papers, 2020 to 2023). A malignant (clonal) hematologic disorder, involving hematopoietic stem cells and characterized by the presence of primitive or atypical myeloid or lymphoid cells in the bone marrow and the blood. "Overexpression of this gene was correlated (in the case of leukemia) with a negative prognosis, patients having multiple relapses, and a short overall survival, whereas suppression of MCM7 gene expression was proposed as a new potential therapy for leukemia." (PMID 31936215, 2020).
pancreatic cancer (2 papers, 2008 to 2014). "AKT2 and MCM7 were overexpressed, and CAMTA2 and PFN1 were underexpressed in pancreatic cancer tissues than in morphologically normal operative margin tissues." (PMID 25502777, 2014).
pituitary adenomas (2 papers, 2017 to 2022). "miR-106b~25 and its host gene MCM7 are potential novel biomarkers for invasive ACTH-immunopositive pituitary adenomas." (PMID 28432562, 2017).
sarcoma (2 papers, 2021 to 2024). A usually aggressive malignant neoplasm of the soft tissue or bone. "Various cancer tissues, including sarcoma and carcinoma cell lines, show overexpression of MCMs, particularly MCM7." (PMID 38182577, 2024). "Analyses using these two datasets also showed the overexpression of MCM7 in sarcoma." (PMID 34239894, 2021). "MCM7 is part of the MCM complex, that plays an important role in cell cycle initiation, and is upregulated in several tumors, including sarcomas." (PMID 38182577, 2024). "We found that except for MCM1, all other MCM factors had higher expression levels in sarcoma than in normal tissues (p < 0.05 for MCM2, MCM4, MCM5, MCM6 and MCM7)." (PMID 34239894, 2021).
Sepsis (2 papers, 2016 to 2023). Sepsis is defined as life-threatening organ dysfunction caused by a dysregulated host response to infection. "In both baboon sepsis models, we observed a gradual decrease of MCM7 in WBCs after induction of sepsis, which did not match the observed dynamics of miR-93-5p." (PMID 37261908, 2023). "miR-93-5p is located within intron 12 of the coding gene minichromosome maintenance complex component 7 (MCM7) at chromosome 7q22.1; hence, we wanted to check whether MCM7 had a similar change in expression after induction of sepsis." (PMID 37261908, 2023).
adenoma (1 paper, 2017). A neoplasm arising from the epithelium. "Examination of MCM7 expression pattern in a series of PAs revealed its significantly higher levels in invasive ACTH-producing adenomas, compared to noninvasive tumors." (PMID 28432562, 2017). "Among residual adenomas, the ones that progressed exhibited significantly higher MCM7 LIs (mean: 36.0 ± 4.0%) than clinically controlled tumors (mean: 16.3 ± 3.9%)." (PMID 28432562, 2017). "The purpose of this study was to assess whether miR-106b~25 and MCM7 levels correlate with tumor invasiveness in a cohort of ACTH-immunopositive adenomas." (PMID 28432562, 2017).
Alzheimer disease (1 paper, 2023). A progressive, neurodegenerative disease characterized by loss of function and death of nerve cells in several areas of the brain leading to loss of cognitive function such as memory and language. "Worth a mention is the downregulation of DDIT3, SMC4, and TENM4 in replicative senescence of human fibroblasts; the upregulation of SMC4 and MCM7 after vitamin C treatment; the upregulation of HOXB3 and TENM4 in Alzheimer’s disease; and the deregulation of DDIT3 and SMC4 in COVID-19 disease." (PMID 36982191, 2023).
anal squamous cell carcinoma (1 paper, 2021). A squamous cell carcinoma (SCC) arising from the anal canal or the anal margin (perianal skin). "Neither MCM7 nor pS6 was as highly upregulated within the area of anal squamous cell carcinoma, as observed in the HSIL lesion." (PMID 34281391, 2021).
benign melanocytic skin nevus (1 paper, 2021). A benign, circumscribed proliferation of melanocytes in the skin. "MCM7 is significantly upregulated in benign melanocytic skin nevus, with fold changes of 8.786 in Talantov’s dataset." (PMID 34490114, 2021).